CYP2D6 (cytochrome P450 family 2 subfamily D member 6 (gene/pseudogene))
Diseases named in the same sentence as CYP2D6 in open-access papers (continued):
Sharing a sentence is not in itself a finding about the gene and the disease.
breast carcinoma (continued). "Swedish breast cancer patients (n = 699) operated 2006–2014, genotyped for CYP2D6, having at least three months postoperative tamoxifen treatment, a baseline, and at least one follow-up digital mammogram were included in the study." (PMID 34570302, 2021). "CYP2D6 has been extensively studied in breast cancer due to its ability to convert tamoxifen to the more active metabolite, endoxifen." (PMID 34597305, 2021). "This is in agreement with our previous report about breast cancer health disparities where AS breast cancer patients experience higher levels of CYP2D6 compared to their CA counterparts." (PMID 34597305, 2021). "We investigated the effect of additional adjuvant systemic therapy and CYP2D6 activity on MD change in a cohort of tamoxifen-treated pre- and postmenopausal breast cancer patients." (PMID 34570302, 2021). "The association between other metabolizing enzymes such as CYP2D6 and SULT1A1 and the clinical response toward tamoxifen therapy in breast cancer patients have been also evaluated in several reports." (PMID 33503040, 2021). "Rather, the biogeographical groups should help to roughly estimate the CYP2D6 functionality-related risk for subtarget CSS,min ENDX in different breast cancer populations and highlight populations with highest need for personalized dosing." (PMID 34069810, 2021). "For example, CYP2D6 polymorphism is involved in tamoxifen variability among patients with breast cancer, since CYP2D6 is involved in tamoxifen metabolization to 4-hydroxytamoxifen and endoxifen, both of which display higher anti-estrogenic activity." (PMID 31936346, 2020). "In a prospective cohort study, 158 breast cancer patients were treated with tamoxifen and received concomitant treatment with CYP2D6 inhibitors." (PMID 32906709, 2020). "Both poor and ultrarapid CYP2D6 metabolizers of tamoxifen have a worse prognosis for breast cancer compared with normal metabolizers after receiving a standard dose of tamoxifen." (PMID 31800347, 2020). "A recent study reported that about 26% of Ethiopian breast cancer patients had germline CYP2D6 amplifications, predicting a significantly increased plasma concentration of endoxifen, the active tamoxifen metabolite, in most cases." (PMID 32872162, 2020). "For these, a high level of evidence is fulfilled only by tamoxifen dosage adjustment for CYP2D6 haplotypes (CYP2D6*1, CYP2D6*10, CYP2D6*3, CYP2D6*4, CYP2D6*41, CYP2D6*5, and CYP2D6*6) in breast cancer." (PMID 32872162, 2020). "Both poor and ultrarapid CYP2D6 metabolizers of tamoxifen have a worse prognosis for breast cancer compared with normal metabolizers." (PMID 31800347, 2020). "It has not previously been shown, with sufficient power and long-term follow-up, that poor and ultrarapid CYP2D6 metabolizers are more likely than normal metabolizers to die as a result of breast cancer." (PMID 31800347, 2020). "Lastly, a neural network model was recently developed and trained on long-read CYP2D6 sequencing data in conjunction with information on the rate of CYP2D6-mediated tamoxifen metabolism from 561 patients with breast cancer." (PMID 33143137, 2020). "CYP2D6*10 is recently observed in both Malay and Chinese while CYP2D6*4 in the Indian ethnic group has been observed among breast cancer patients." (PMID 31900126, 2020). "We genotyped CYP2D6 in 1,309 patients with breast cancer who were treated with tamoxifen and were diagnosed from 2005 to 2012; they were categorized as poor, intermediate, normal, or ultrarapid CYP2D6 metabolizers." (PMID 31800347, 2020). "CYP2D6 IM/PMs have been associated with reduced endoxifen plasma concentration, although the evidence relating CYP2D6 to clinical outcomes indicative of reduced tamoxifen efficacy, such as breast cancer recurrence and mortality, are inconsistent." (PMID 33143137, 2020).
breast carcinoma (continued). "For women with breast cancer, potential interference of antidepressants with tamoxifen has been reported since some SSRIs and SNRIs can inhibit CYP2D6 enzyme with a consequent decrease in the formation of the active metabolite from inactive tamoxifen." (PMID 31123492, 2019). "The present analysis takes a specific clinical context: Portuguese women with breast cancer (BC), and evaluates the possible impact of genotyping tests for CYP2D6 relative to tamoxifen." (PMID 31284530, 2019). "Recently, genotyping of CYP2D6 in patients undergoing tamoxifen therapy for premenopausal and postmenopausal breast cancer patients has been proposed to improve treatment outcome." (PMID 31178724, 2019). "Our investigations of mistletoe interactions with CYP3A4/5 and CYP2D6, secure recommendations for the use of mistletoe extracts to treat cancer related-fatigue in breast cancer patients receiving tamoxifen." (PMID 30658716, 2019). "This research study proposed itself to investigate the impact of genetic testing for CYP2D6 in relation to tamoxifen in the management of women with breast cancer, within a specific hospital European Union (EU) country context." (PMID 31284530, 2019). "Recently, the CPIC has also published guidelines focusing on the role of CYP2D6 genotype in the adjuvant treatment of estrogen receptor-positive breast cancer." (PMID 30328952, 2018). "First, we examined the effect of tamoxifen treatment for a first primary breast cancer on the risk of CBC, according to the individual CYP2D6 AS levels." (PMID 30526633, 2018). "The present study aimed to review recent findings related to the impact of CYP2D6 polymorphisms and how they can affect the results of TMX in breast cancer treatment." (PMID 30536272, 2018). "The keywords CYP2D6, tamoxifen, and breast cancer were searched in the PubMed, Scopus, The Cochrane Library, Scielo, and Bireme databases." (PMID 30536272, 2018). "Use of the CVD multi-gene test excluded the most prevalent CYP2D6 null-allele in Caucasians (CYP2D6*4), while homozygosity of MTHFR 677 C>T was detected in both the index case and her daughter with the luminal-type breast cancer." (PMID 28241424, 2017). "Our aim was to investigate the predictive value of direct measurements of active serum tamoxifen metabolites in patients with operable breast cancers and to compare these results with the CYP2D6 genotyping method." (PMID 29183390, 2017). "CYP2D6 have been intensively studied, but the role of CYP2C19 is less elucidated, and we studied the association of CYPC19 genotype and recurrence of breast cancer." (PMID 28798474, 2017). "Although our study does not provide direct data for clinical outcome prediction, an endoxifen threshold concentration of 5.9 ng/mL useful to predict breast cancer recurrence risk during TAM therapy is predictable by CYP2D6." (PMID 28955222, 2017). "Tamoxifen, a common anti-estrogen breast cancer medication, is a prodrug that undergoes bioactivation via cytochrome P450 enzymes, CYP2D6 and to a lesser degree, CYP3A4 to form the active metabolite endoxifen." (PMID 27169677, 2016). "SSRIs and, in particular, fluoxetine and paroxetine as the strongest CYP2D6 inhibitors, may therefore prevent the formation of the active metabolite from inactive tamoxifen and put breast cancer patients under anti-oestrogenic treatment at an increased risk of breast cancer recurrence." (PMID 25713759, 2015). "Homozygote-poor metabolisers for CYP2D6 tended to have a higher rate of breast cancer recurrence with continued tamoxifen use (OR 2.40; 95% CI 0.86-6.66, p = 0.09)." (PMID 25713759, 2015). "Blood samples from 279 Polish women with breast cancer receiving tamoxifen 20 mg daily were analyzed for CYP2D6 genotype and drug metabolite concentration." (PMID 26232141, 2015).
breast carcinoma (continued). "For example, some SSRIs, which are used in up to 30 % of breast cancer patients for depression or the relief of tamoxifen-induced menopausal symptoms such as hot flashes, were found to be strong CYP2D6 inhibitors." (PMID 26232141, 2015). "The inhibition of CYP2D6 decreases tamoxifen metabolism and adversely affects the efficacy of breast cancer treatment." (PMID 24886861, 2014). "Overall the allele frequencies were very similar to those observed herein, except for CYP2D6*4 which was observed in 18% of breast cancer patients." (PMID 25329392, 2014). "Another retrospective patient cohort also showed that decreased CYP2D6 metabolism results in increased rates of breast cancer recurrence and decreased relapse-free survival time." (PMID 24886861, 2014). "Based on clinical studies there is an increasing body of evidence that the in vivo metabolism of tamoxifen in postmenopausal early breast cancer depends on CYP2D6, thereby altering tamoxifen response." (PMID 24936398, 2014). "In conclusion, we suggest that co-administration of endoxifen in tamoxifen treated early breast cancer women with impaired CYP2D6 metabolism is a promising alternative to reach plasma concentrations comparable to CYP2D6 EM patients." (PMID 24936398, 2014). "Here, we present a PBPK model-based virtual clinical trial for CYP2D6 phenotype-dependent dosing of tamoxifen plus the concomitant use of endoxifen in early postmenopausal breast cancer." (PMID 24936398, 2014). "Inhibition of CYP2D6 decreases tamoxifen metabolism and adversely affects the efficacy against breast cancer treatment." (PMID 24886861, 2014). "The large body of data evaluating the prognostic and predictive relevance of CYP2D6 gene testing to guide tamoxifen therapy for breast cancer was inconsistent, and the CPMC chose to present these to the PAG for specific guidance." (PMID 24134832, 2013). "A meta-analysis published by Seruga and Amir (2010) analyzed data from 10 studies assessing CYP2D6 genotype and clinical outcomes in breast cancer." (PMID 23346096, 2012). "The first therapeutic target to drive the attention of pharmacogenetic studies to breast cancer therapy was CYP2D6 in view of its apparent strong genotype-phenotype correlation." (PMID 23346096, 2012). "CYP2D6 (cytochrome P450, family 2, subfamily D, polypeptide 6) genotyping and its influence on breast cancer treatment by tamoxifen indicate the importance of personalized medicine in treating patients." (PMID 25562699, 2012). "The evaluation of studies involving chemotherapeutic protocols for breast cancer therapy indicates that many xenobiotic metabolizing enzymes other than CYP2D6 are also being considered as possible pharmacogenetic targets." (PMID 23346096, 2012). "Participants were enrolled in an informational session that reviewed the results of studies of CYP2D6 genotype on breast cancer recurrence." (PMID 21970596, 2011). "CYP2D6 genotyping was performed in 282 primary breast cancer patients, including 67 patients reported previously." (PMID 27713292, 2010). "In one example, thirty five CYP2D6 genotypes were partitioned into three groups to predict pharmacokinetics of a breast cancer drug, Tamoxifen, a CYP2D6 substrate (p-value = 0.04)." (PMID 20467479, 2010). "Studies are underway to determine the utility of CYP2D6 genotyping for making clinical decisions about tamoxifen and the potential to optimize breast cancer therapy." (PMID 21037853, 2010). "We investigated the effect of reduced CYP2D6 genotype on the response to TAM in patients with familial early-onset breast cancer." (PMID 27713292, 2010). "A total of 1,361 hormone receptor positive (estrogen receptor– positive and/or progesterone receptor– positive) breast cancer patients treated with adjuvant TAM monotherapy were genotyped for CYP2D6*3, *4, *5, *10, *41 and duplications." (PMID 27713292, 2010).
breast carcinoma (continued). "A subsequent study on the same study population reported that co-prescription of CYP2D6 inhibitors, in addition to CYP2D6 genetic variation, was an independent predictor of breast cancer outcome in postmenopausal women receiving TAM." (PMID 27713292, 2010). "Breast cancer patients who were poor metabolizers of CYP2D6 had a worse clinical outcome and fewer adverse effects compared with those who were extensive metabolizers of CYP2D6." (PMID 21876648, 2008). "This study investigated the susceptibility and prognostic implications of the CYP2E1, CYP2C19, CYP2D6, mEH and NAT2 gene polymorphisms in breast carcinoma patients." (PMID 18423013, 2008). "In this study, mEH gene polymorphism was also associated with the early onset of breast carcinoma whereas polymorphisms in NAT2 and CYP2D6 genes are also correlated with late onset of breast carcinoma." (PMID 18423013, 2008). "Several studies highlighted the role of XME gene polymorphisms such as CYP1A1, CYP1B1, CYP2D6, mEH, GSTT1, GSTM1 and NAT1 in treatment efficacy as well as survival after treatment of breast carcinoma." (PMID 18423013, 2008). "Previous studies have suggested that CYP2D6 inhibitors such as paroxetine may impair the conversion of tamoxifen into its active form and hinder its efficacy in treating breast cancer." (PMID 38554178, 2025). "In this context, at present, females with breast cancer who are CYP2D6 poor metabolizers should be considered for alternative treatments to tamoxifen; if none are available, the daily tamoxifen dose could be increased." (PMID 40452016, 2025). "We also found CYP2D6*4 carriers had 1.76- and 3.7-fold worsening of overall and breast cancer-specific survivals, respectively, while *4 homozygotes had a striking 11-fold increase in breast cancer-specific mortality." (PMID 40452016, 2025). "A retrospective study of early breast cancer with a median 6.3-year follow-up found that carrying a reduced or non-functional CYP2D6 allele was associated with worse tamoxifen outcomes." (PMID 40452016, 2025). "The endoxifen plasma concentration was lower in CYP2D6 IMs than in NMs, but these variants did not compromise the adverse effects of tamoxifen in Asian patients with breast cancer." (PMID 40050768, 2025). "Future research could also investigate the feasibility of implementing endoxifen monitoring and CYP2D6 phenotyping in clinical settings for breast cancer patients, followed by the cost-effectiveness evaluation." (PMID 40137409, 2025). "However, data on the distribution of CYP2D6 genotypes in ER+ breast cancer patients in Indonesia are missing." (PMID 40137409, 2025). "We measured the association between pharmaceutical inhibition of CYP2D6, CYP2C19, and CYP3A4 and recurrence in a large cohort of tamoxifen‐treated Danish premenopausal breast cancer patients using a Bayesian joint modeling approach and compared this with traditional Cox regression models." (PMID 40364655, 2025). "We hypothesised that the polymorphisms of the CYP2D6 and CYP2C19 genes can affect the efficiency of tamoxifen in the treatment of patients with breast cancer." (PMID 38681733, 2024). "However, a study found that toremifene was superior to tamoxifen in adjuvant endocrine treatment for CYP2D6 *10 T/T breast cancer patients." (PMID 39286777, 2024). "Decreased CYP2D6 activity or the use of CYP2D6 inhibitors may reduce the clinical efficacy of tamoxifen and lead to an increased recurrence rate of breast cancer." (PMID 38352696, 2024). "Additionally, SNRIs can interfere with the cytochrome P450 2D6 (CYP2D6) enzyme required for the metabolism of tamoxifen, a breast cancer therapy." (PMID 38371081, 2024). "CYP2D6 metabolizes up to 30% of drugs commonly used in clinical practice and metabolizes tamoxifen and tramadol, which are both frequently used in the management of breast cancer in Southern Africa." (PMID 37623436, 2023).
breast carcinoma (continued). "Other three studies also reported negative results on the association of CYP2D6*10 and survival of the breast cancer patients (OS, DFS, RFS, BCSS) (Refs 48, 67, 73)." (PMID 34991754, 2022). "Moreover, the CYP2D6 genotypes can predict Tamoxifen discontinuation and prognosis in patients with breast cancer." (PMID 36467027, 2022). "Moreover, pharmacogenetic studies assessing the influence of CYP2D6 genotypes on tamoxifen efficacy in breast cancer patients from this region are rather scarce." (PMID 36243690, 2022). "Our findings demonstrate a lack of association between CYP2D6 phenotype and clinical outcomes in Syrian breast cancer patients receiving adjuvant tamoxifen therapy." (PMID 36243690, 2022). "Our aim was to investigate the effect of CYP2D6 activity and additional systemic treatment, including chemotherapy, GnRH-analogs and switch to aromatase inhibitors, on MD change, in a cohort of tamoxifen-treated pre- and postmenopausal breast cancer patients." (PMID 34570302, 2021). "Therefore, the primary objective of this review is to discuss new data on CYP2D6 genotyping in breast cancer patients treated with tamoxifen." (PMID 33673305, 2021). "Despite the large potential of MIPD, it is important to mention that the relationship between CYP2D6 genotype and/or endoxifen concentrations and breast cancer recurrence is still controversial and has been the subject of intensive debates amongst researchers and clinicians since almost a decade." (PMID 32296331, 2020). "Furthermore, in breast cancer, the region on chromosome 22 that contains CYP2D6 is commonly deleted." (PMID 33143137, 2020). "The potential role of CYP2D6 genotype assessment in determining whether breast cancer patients should receive TAM is controversial." (PMID 31852530, 2019). "Some authors have demonstrated that such polymorphisms on CYP2D6 gene are not to be associated with survival in breast cancer patients." (PMID 31284530, 2019). "Another key question that needs to be answered before clinical validation and that is whether the cost-effectiveness of genetic testing for CYP2D6 as a management option in women with breast cancer is viable." (PMID 31284530, 2019). "This study investigates the influence of menopausal status on the pharmacokinetics of TAM and its metabolites END, 4-HTAM and NDTAM in TAM-treated breast cancer patients phenotyped as NMs for CYP2D6 and with CYP3A activity based on the oral midazolam clearance." (PMID 31852530, 2019). "In the present study, we investigated the pharmacokinetics profile and the influence of CYP2D6, CYP2C9, CYP2C19, CYP3A5, POR, ABCB1 and UGT2B15 polymorphisms on the plasma level of tamoxifen and its active metabolites in Ethiopian breast cancer patients receiving adjuvant tamoxifen." (PMID 31547390, 2019). "Therefore, we aim to investigate the impact of CYP2D6 genotyping of the tamoxifen metabolizing enzymes in the clinical management of breast cancer patients." (PMID 31284530, 2019). "Taken together, for the first time we showed that the concept of dose escalation of tamoxifen in CYP2D6 compromised breast cancer patients is feasible in an Iranian population resulting in significantly higher plasma concentrations of the active metabolite (Z)-endoxifen." (PMID 31178724, 2019). "Since our findings suggest that CYP2D6 phenotype may impact the effectiveness of tamoxifen for prevention of second primary breast cancers, it may also be relevant with regards to the use of tamoxifen as a chemopreventive agent among high-risk women." (PMID 30526633, 2018). "We have reported the diversity of polymorphism frequencies for the CYP2D6, CYP3A5, CYP2C8, and IL-10 genes in breast cancer patients from Mexico and Spain and classified them by metabolic activity for chemotherapy but no specific function has been described for these polimorphisms." (PMID 29997359, 2018).